EGF (epidermal growth factor)
Diseases named in the same sentence as EGF in open-access papers (continued):
Sharing a sentence is not in itself a finding about the gene and the disease.
adenoma (18 papers, 2000 to 2023). A neoplasm arising from the epithelium. "While large intestinal organoids require WENR for growth in vitro, adenoma organoids require only addition of EGF and Noggin (EN) to basic media for their growth in culture." (PMID 35260534, 2022). "Overexpression of FZD9, a receptor to Wnt proteins, further links adenomas from female patients with EGF, as the EGFR pathway interacts with Wnt/ßcatenin signalling." (PMID 32183012, 2020). "To understand the basis for the heightened proliferative state of EGF-treated adenoma cells upon LGR5 suppression, we next analysed cell cycle status." (PMID 29149105, 2018). "To assess the effect of EGF on LGR5+ cells at an early stage of CRC we required a physiologically relevant in vitro adenoma model that exhibited EGF-sensitivity." (PMID 29149105, 2018). "LGR5+ cells are known to exist outside the stem cell niche during CRC progression, and the requirement for epidermal growth factor (EGF) signalling within early adenomas remains to be fully elucidated." (PMID 29149105, 2018). "Epidermal growth factor and gefitinib treatments were performed in EGF-responsive LGR5+ early adenoma RG/C2 cells." (PMID 29149105, 2018). "Taken together these data indicate that suppression of LGR5 enhances the proliferative capacity of EGF-treated adenoma cells." (PMID 29149105, 2018). "EGF-treated adenoma cultures contained a significantly higher proportion of cells in the S-phase or G2/M stages of the cell cycle, relative to control siRNA-treated cultures at both 24 and 48 h." (PMID 29149105, 2018). "EGF-treated adenoma cells exhibited a significantly higher level of Ki67 protein at both 24 and 48 h relative to control as expected given the growth response of RG/C2 cells to this mitogen." (PMID 29149105, 2018). "Similar to normal murine organoids, we noted an increase in LGR5 expression following EGF withdrawal from 3D adenoma culture medium." (PMID 29149105, 2018). "To understand the basis for the reduced survival of EGF-treated adenoma cells upon LGR5 knockdown, we next examined expression levels of the Ki67 proliferation marker." (PMID 29149105, 2018). "Suppression of LGR5 reduces the survival of EGF-treated adenoma cells by increasing detached cell yield but also inducing a proliferative state, as evidenced by elevated Ki67 level and enhanced cell cycle progression." (PMID 29149105, 2018). "In addition, the oncogenic activation of KRAS leads to the independency of the adenoma cells from external epidermal growth factor (EGF) activity." (PMID 32775326, 2020). "Furthermore, LGR5 silencing in adenoma cells enhances the proliferative state of EGF-treated adenoma cells, as observed by induction of Ki67 expression, enhanced cell cycle progression and reduced survival." (PMID 29149105, 2018). "LGR5 has an important role in the EGF-mediated survival and proliferation of early adenoma cells and could have clinical utility in predicting response of CRC patients to EGFR therapy." (PMID 29149105, 2018). "EGFR and its ligand EGF are highly expressed in corticotroph adenoma cells in up to 75% of corticotroph tumors as well as normal pituitary cells, gonadotroph, somatotroph, and lactotroph adenoma cells." (PMID 28529722, 2017). "On the other hand, among genes overexpressed in adenomas from female patients, AKAP12 (gravin) is a known tumour suppressor and SLC9A9 is associated with epidermal growth factor (EGF) receptor turnover, EGF itself notably involved in corticotrope tumourigenesis." (PMID 32183012, 2020). "Therefore, inhibiting both COX-2 as well as the PPAR and TGF/EGF pathway could be effective in the inhibition of adenoma or even carcinoma development in the intestine." (PMID 17955050, 2007). "We obtained crypts from the intestines of these mice (including adenomas) and derived intestinal organoids in the absence of R-Spondin (EN medium, EGF + Noggin)." (PMID 35314684, 2022).
adenoma (continued). "Given the enhanced proliferative response to EGF with LGR5 silencing, we next investigated whether this could sensitise adenoma cells to EGFRi." (PMID 29149105, 2018). "Moreover, EGF suppresses the expression of LGR5 (a co-receptor for Wnt/β-catenin signaling and marker of both normal intestinal stem cells and cancer stem cells) finely regulated during the adenoma-carcinoma progression, the development and maintenance of CRC-derived metastasis." (PMID 37853459, 2023).
endometriosis (18 papers, 2015 to 2025). The growth of functional endometrial tissue in anatomic sites outside the uterine body. "EGF has been implicated in the pathogenesis of endometriosis due to its well-known roles in cell proliferation, differentiation, and migration; however, limited data are available regarding its systemic and tissue-specific levels in this disease." (PMID 40724945, 2025). "EGF, involved in tissue remodeling and cellular proliferation, is dysregulated in endometriosis and has been associated with cell migration and invasion." (PMID 40724945, 2025). "We found that EGF showed a strong positive correlation with DM and dysuria in patients with mild endometriosis, suggesting that serum EGF levels are associated with reduced pain symptoms in mild disease." (PMID 40724945, 2025). "Another study revealed upregulated genes like EGF and IL-1β in endometriosis, associated with focal adhesion and calcium signaling, implicating them in endometriosis pathogenesis." (PMID 39108650, 2024). "Interestingly, the initial induction of endometriosis was associated with activation of epidermal growth factor (EGF) signalling in the eutopic endometrium of the baboon model and EGF signalling was associated with up-regulation of TA in normal ovarian surface epithelial cells." (PMID 27979878, 2017). "In patients with mild endometriosis, EGF showed a strong positive correlation with dysuria (r = 0.8; p = 0.048)." (PMID 40724945, 2025). "The serum EGF levels were significantly lower in patients with endometriosis (stages I–IV) than those in healthy controls, with the most pronounced decrease observed in the mild stages of the disease." (PMID 40724945, 2025). "We present the first data on disease severity-associated changes in the serum levels of the growth factor EGF, the inflammatory cytokines MIF and IL-6, and the inhibitory sensory neuropeptide SOM in patients with endometriosis." (PMID 40724945, 2025). "The expression of IL-2, IL-17A, and EGF was higher in the non-endometriosis group than in the eutopic endometrium group." (PMID 35269619, 2022). "Differential signaling networks between Endometriomas and Endometriosis suggested that EGF may be more enriched in Endometriosis, while VEGF was similarly enriched in both tissue types." (PMID 41159025, 2025). "Serum EGF was significantly lower in mild endometriosis and in the secretory phase." (PMID 40724945, 2025). "E2+P4 elicited, only in eSFstage-I, several distinct functional clusters with specific functions in endometrial biology and endometriosis, including EGF/EGF-like genes, ECM receptor interaction, focal adhesion, PI3K-Akt pathway, synapse, cell junctions, spectrins and others." (PMID 32555663, 2020). "In addition, EGF levels were lower in the secretory phase of endometriosis patients (ENDO SEC group) than in the secretory phase of healthy individuals (CTRL SEC group), in the proliferative phase (ENDO PROL group), and in endometriosis patients without a menstrual cycle (NC group)." (PMID 40724945, 2025). "Notably, we showed that vitamin D3 significantly reduced PDGFB and EGF gene expression, indicating that vitamin D supplementation might be a therapeutic approach to managing endometriosis." (PMID 38698459, 2024). "Platelets play a critical role in endometriosis-associated fibrogenesis: activated platelets within lesions release numerous growth factors, cytokines, and chemokines such as TGF-β1, platelet-derived growth factor (PDGF), epidermal growth factor (EGF), and connective tissue growth factor (CTGF)." (PMID 36289173, 2023). "In another empirical study, we indicated that endometriosis is characterized by an upregulation in the expression of the PDGFB and EGF at the gene level." (PMID 38698459, 2024). "The PPI network analysis reveals hub genes, including BCL2, CCNA2, CDK7, EGF, GAS6, MAP3K7, and TAB2, which emerge as pivotal players in endometriosis progression." (PMID 39108650, 2024).
endometriosis (continued). "The available research suggested that platelets played a vital role in endometriosis-related fibrosis by releasing significant amounts of growth factors, cytokines, and chemokines (e.g., TGF-β1, PDGF, EGF, CTGF) when activated within the lesion." (PMID 38735939, 2024). "Furthermore, EGF and SOM levels were significantly corelated with DM and dysuria in patients with mild endometriosis, suggesting a potential link between these mediators and pain symptoms independent of hormonal status." (PMID 40724945, 2025). "In conclusion systemic EGF, MIF, IL-6, and SOM might have a contribution to the development and symptomatology of endometriosis, but further rigorous and standardized research is needed to clarify their roles in disease development." (PMID 40724945, 2025). "However, further studies are necessary to elucidate the precise roles of EGF and EGFR in endometriosis and related pain." (PMID 40724945, 2025). "Furthermore, factors modulating its secretion (localized hypoxia, IL-1β, TGF-β, EGF and PGE2) are increased in the case of endometriosis." (PMID 36979957, 2023). "Moreover, endometriosis cell lines with low EGF secretion show more dedifferentiated rather than proliferative properties." (PMID 40724945, 2025). "There is no doubt that endometriosis patients show elevated levels of expression and release of a range of proinflammatory cytokines and growth factors, including IL-1, IL-6, IL-8, epidermal growth factor and hepatocyte growth factor, in their ectopic and eutopic endometrium and peritoneal fluid." (PMID 36359004, 2022).
lung fibrosis (18 papers, 2007 to 2026). "Its receptor is extensively presented in postmortem lung tissue samples from patients with COVID-associated pneumonia, as EGF seems to be involved in the formation of lung fibrosis in severe cases." (PMID 36430621, 2022). "Overall, angiogenic proteins implicated in tissue injury and fibrosis (TGF-β1, FGF-2, EGF, and HB-EGF) were maintained at euthermic levels during torpor, so it is unlikely that there is any lasting lung fibrosis or injury in hibernating animals." (PMID 31763078, 2019). "Although lots of cytokines were regulated independently of HBoV status, several cytokines associated with lung fibrosis and tumour development, e.g., EGF, VEGF, TARC (CCL17), TNF-α, TNF-β, TIMP-1, were clearly upregulated in the HBoV-positive cohort." (PMID 26807786, 2016). "Stat1 KO mice are also susceptible to bleomycin-induced lung fibrosis with heightened proliferative responses to growth factors such as platelet-derived growth factor (PDGF) and epidermal growth factor (EGF)." (PMID 33022979, 2020). "Afterward, we used Metascape for the pathway enrichment analysis of this network, and we found that the most significant terms within the cluster consisting of EGF, IL-1β, IL-3, TNF-α, CCL2 were associated with lung fibrosis and proinflammatory/fibrotic mediators." (PMID 36733673, 2023). "EGF may play an important role in pulmonary fibrosis after SARS-CoV-2 infection." (PMID 33726831, 2021). "EGF, a canonical ligand of EGFR, which mediates an important signaling axis for the development of lung fibrosis, was also found to be significantly increased in these supernatants." (PMID 38976646, 2024). "Fibroblast growth factors (FGFs) have an important role in the regulation of airway remodeling, with members of the EGF and FGF family playing a part in persistent inflammation and tissue repair processes, leading to pulmonary fibrosis." (PMID 38540990, 2024). "We observed that EGF significantly enhanced FAPs fibrogenic differentiation, aligning with previous studies that have characterized EGF signaling in the expansion of the ECM in other tissues and diseases, such as cancer or pulmonary fibrosis." (PMID 41513629, 2026). "So, it is of great significance to study EGF function in SARS-CoV-2 infected body, which may help prevent pulmonary fibrosis and learn further about the pathogenesis of SARS-CoV-2 induced lung injury." (PMID 33726831, 2021). "EGF is a ligand for EGFR, and activation of EGFR is related to pulmonary fibrosis in lung disease." (PMID 31333459, 2019). "Although there is no established correlation between EGF and fibrotic signaling in the context of LF hypertrophy, based on studies in pathologies such as cancers and lung fibrosis, understanding the EGF signaling in the LF could foster the development of novel therapeutic strategies in the future." (PMID 39456209, 2024).
atherosclerosis (17 papers, 2013 to 2025). A disease characterized by the build-up of fatty material and calcium deposition in the arterial wall resulting in partial or complete occlusion of the arterial lumen. "Despite the role of EGF in atherosclerosis, our paper is the first to assess the association of the known functional polymorphism rs444903 with the severity of coronary atherosclerosis." (PMID 27835972, 2016). "Heparin-binding epidermal growth factor (EGF)-like growth factor (HBEGF) level was reported as a correlation with the formation of atherosclerosis through regulating IL-8 expression." (PMID 37373979, 2023). "In contrast to polymorphisms in FGF2 and EGF, polymorphism rs35767 in the IGF1 gene was studied in the context of atherosclerosis; however, data are scarce." (PMID 27835972, 2016). "For instance, an adenine to cytosine substitution at cDNA position 561, resulting in an amino acid exchange from serine (Ser) to arginine (Arg), in the epidermal growth factor (EGF) -like domain of E-selectin has profound effects on atherosclerosis." (PMID 24498435, 2014). "VEGF and EGF also attract monocytes and are involved in progression of atherosclerosis." (PMID 23984427, 2013). "Cocaine may lead to accelerated atherosclerosis via platelet activation and subsequent release of mitogens such as platelet-derived growth factor, epidermal growth factor, and transforming growth factor-beta." (PMID 23984119, 2013). "Among these, expression of the KD gene Mfge8 (milk fat globule EGF and factor V/VIII domain containing) of GRNMAGENTA was significantly downregulated in late-stage atherosclerosis in male mice, while expression was maintained in female plaques." (PMID 37589136, 2023). "The current results demonstrated thatET-1 enhanced CHSY1 level expression in VSMCs.Also, EGF and TGF-β, both which are known to beinvolved in the atherosclerosis development, up-regulatesCHSY1 level." (PMID 34837677, 2021). "Heparin binding EGF-like growth factor (HB-EGF), which is a member of epidermal growth factor (EGF) family member and a ligand for EGF-receptor (EGFR), is involved in various pathophysiological processes including atherosclerosis and cancer development." (PMID 28792970, 2017). "Finally, the mice ortholog of key driver gene MFGE8 (milk fat globule EGF and factor V/VIII domain containing) showed retained expression in advanced plaques from female mice but was downregulated in male mice during atherosclerosis progression." (PMID 37589136, 2023). "Growth factors such as bFGF, EGF, IGF-1, PDGFB, TGF-β1 and VEGF-A play important roles in VSMC and EC migration and proliferation, therefore playing important roles in the pathogenesis of atherosclerosis." (PMID 27835972, 2016). "Growth factors [transforming growth factor-β (TGF-β), epidermal growth factor (EGF), endothelin-1 (ET-1)] stimulate proteoglycan synthesis resulting in retention and accumulation of low density lipoprotein (LDL) in vesselintima and leading to atherosclerosis development." (PMID 34837677, 2021).
sarcoma (17 papers, 2011 to 2025). A usually aggressive malignant neoplasm of the soft tissue or bone. "Both matrices are derived from Engelbreth-Holm-Swarm mouse sarcoma, and contain growth factors (EGF, FGF, TGFβ, IGF), ECM proteins (laminin, collagen IV, entactin), proteases (MMP-2, MMP-9), and perlecan." (PMID 30805306, 2019). "We chose bFGF and EGF, both widely used in organoid protocols, and IGF1, as the IGF1R pathway plays a crucial role in EwS and other sarcoma entities." (PMID 40841513, 2025). "Matrigel is the solubilized basement membrane matrix secreted by Engelbreth–Holm–Swarm (EHS) mouse sarcoma cells, which contains laminin, nidogen, collagen and heparan sulfate proteoglycans as well as growth factors such as TGF-beta and EGF." (PMID 40416648, 2025). "This scenario represents a novel role for EGF and CTGF as regulators of the Fas pathway in sarcomas." (PMID 22135505, 2011). "Herein, we propose that EGF and CTGF play essential roles in the regulation of the Fas apoptotic pathway in sarcomas." (PMID 22135505, 2011). "The seven shared pathways were integrin signalling, inflammation-mediated signalling, cytoskeletal regulation by Rho GTPases, rat sarcoma (Ras) signalling, fibroblast growth factor (FGF) signalling, epidermal growth factor (EGF) signalling and the p38 MAPK signalling pathways." (PMID 39057060, 2024). "Furthermore, the observations that EGF stimulation significantly increased protein expression of pAKT and pERK, but not pSTAT3, indicated that both AKT and ERK pathways in sarcomas may be mainly stimulated by EGF/EGFR activation." (PMID 26909593, 2016).